TNF (tumor necrosis factor)
Diseases named in the same sentence as TNF in open-access papers (continued):
Sharing a sentence is not in itself a finding about the gene and the disease.
liver fibrosis (continued). "PA stimulates macrophage production of miR-3064-5p to mediate metabolic inflammation in hepatocytes and adipocytes; TNF-α induces miR-222 to regulate downstream protein expression or act as a new biomarker of liver fibrosis." (PMID 40435202, 2025). "Initially, through network pharmacology, we predicted that the top three key proteins targeted by YQHX in alleviating liver fibrosis were IL-1β, IL-6, and TNF-α." (PMID 41296792, 2025). "IL-17A has been shown to stimulate the activation of HSCs and contribute to liver fibrosis by increasing the expression of pro-inflammatory cytokines, such as IL-6, IL-1β, and TNF-α, as well as pro-fibrotic factors like TGF-β and α-SMA." (PMID 39995661, 2025). "CCl4 triggers an inflammatory response in the liver by increasing the production of inflammatory factors such as tumor necrosis factor (TNF), interleukin (IL)-1β, and IL-6, which are essential to liver fibrosis." (PMID 39968080, 2025). "Hepatic macrophages, including KC- and BMDM-derived TNF-α and IL-1β, also enhance liver fibrosis by promoting aHSCs survival in an NF-κB-dependent manner." (PMID 40761743, 2025). "Previous studies indicate a TNF-α-mediated link between necroptosis and hepatic fibrosis during aging." (PMID 40418410, 2025). "We evaluated the following indicators by immunohistochemical staining to evaluate the degree of inflammation during liver fibrosis: IL-1β, IL-6, Antigen Ki67, and TNF-α." (PMID 40143016, 2025). "Our results showed that MIF was important for the synthesis of the proinflammatory cytokines IL-6 and TNF in the myocardium in a model of TAA-induced liver fibrosis." (PMID 41020850, 2025). "Studies suggest that in liver fibrosis, QR significantly reduces the expression of pro-inflammatory cytokines, including TNF-α and IL-6." (PMID 40076811, 2025). "M1 macrophages represent high expression of CD86, CD68, and iNOS, and secrete the pro-inflammatory factors such as TNF-α, IL-6, and ROS, that exacerbate the hepatic inflammation and tissue injury and promote the development of hepatic fibrosis." (PMID 41375167, 2025). "The serum aminotransferase (ALT and AST), alkaline phosphatase (ALP), bilirubin (TBIL and DBIL), bile acid, inflammatory cytokines (IL-6, IL-1β, TNF-α) and liver fibrosis indicator (HA, LN, PC-III and IV-C) concentrations were measured by ELISA kits." (PMID 41293246, 2025). "In the MASH model, LGG primarily exerted its effects by inhibiting the TGF-β/SMAD signaling pathway and reducing the expression of pro-inflammatory factors (e.g., IL-1β, IL-6, TNF-α), thereby mitigating liver fibrosis and inflammation." (PMID 40778202, 2025). "And DNTs with high expression of TNF-α promote the activation of HSCs and exacerbate hepatic fibrosis through the TNFR1-NLRP3." (PMID 40761743, 2025). "The bioinformatics analysis indicated that TNF, IL-6, PPARG and MMP9 were promising candidate genes that can serve as diagnostic and prognostic biomarkers for liver fibrosis." (PMID 39869574, 2025). "GEN had an effect on improving acetaminophen (APAP)-induced liver damage and hepatic fibrosis in mice by reducing the expressions of connective tissue growth factor, TNF-α and IL-6." (PMID 39512816, 2024). "Studies have reported that Liuweiwuling tablets can alleviate bile-duct ligation-induced liver fibrosis mainly by inhibiting the expression of the inflammatory cytokines IL-1β1, TNF-α, and IL-6." (PMID 38195573, 2024). "M1 macrophages secrete inflammatory cytokines, including TNF-α and IL-1, which induce the transformation of HSCs into myofibroblasts, thereby contributing to the progression of liver fibrosis." (PMID 39717848, 2024). "Because inflammatory cytokines play crucial roles in the development and progression of hepatic fibrosis, we quantified IL-1β, IL-6, and TNF-α levels using ELISA kits." (PMID 38434258, 2024).
liver fibrosis (continued). "GLA can also reduce the levels of inflammatory factors that are closely related to the gut microbiota, such as TNF-α, TGF-β, and ROS, thereby reducing the extent of liver fibrosis and addressing the imbalance of intestinal flora caused by liver diseases." (PMID 39234554, 2024). "After LPS induction, the content of TNF- α in activated HSCs-T6 increased by 40% compared with the steady state, indicating that liver fibrosis would lead to the release of TNF-α." (PMID 38576476, 2024). "Our current study confirmed the anti-inflammatory effects of vitamin D supplementation on mice with liver fibrosis through reductions in IL-1β, IL-4, IL-6, and TNFα in addition to OPN." (PMID 39654627, 2024). "Treatment with phyllanthin was found to improve liver fibrosis by reducing the levels of TNF-α, NF-κB, and TGF-β1 in liver tissue." (PMID 39185304, 2024). "These inflammatory macrophages produce TGF-β to activate HSCs, as well as TNF-α to defenestrate LSECs, which contributes to liver fibrosis and portal hypertension." (PMID 38713515, 2024). "Next, we aimed to examine the expression of TNF-α in liver tissue of different mice groups since it is an important mediator of murine granuloma formation and hepatic fibrosis." (PMID 39439825, 2024). "Generally speaking, BMP at low and medium doses played a role in the treatment of liver fibrosis by down-regulating TNF-α." (PMID 38576476, 2024). "MT was demonstrated to produce an antioxidant influence protecting the hepatocytes from free radical injury and inhibiting pro-inflammatory cytokines such as TNF-α and IL-1β, retarding the development of liver fibrosis." (PMID 38540717, 2024). "TGF-β signaling plays an important role in cell damage; oxidative stress, liver fibrosis, and enhanced TNF-α, TGF-β, and NF-κB expressions were often reported as the primary cause for various hepatotoxic drug-induced liver injuries." (PMID 38313882, 2024). "It was found that the use of curcumin can reduce the TNF-α of hepatic fibrosis mice model by 84.25ng/L (p = 0.001)." (PMID 38781262, 2024). "On the other hand, there is also an aspect that enhances the production of proinflammatory cytokines such as TNF-α and IL-1β, worsening liver fibrosis." (PMID 39316687, 2024). "Further research found that the increased CRP, IL-1β, and TNF-α were significantly associated with MASH and hepatic fibrosis." (PMID 39605886, 2024). "In the phenomapping analysis of HFpEF, one of phenogroups demonstrated high proinflammatory biomarkers including tumor necrosis factor-alpha-mediated inflammation, liver fibrosis, and tissue remodeling." (PMID 38443672, 2024). "The inflammatory mediator TNF-α and its downstream target NF-κB are expressed in different liver cell types and are involved in liver fibrosis." (PMID 38033027, 2023). "In the present study, the productions of IL-6, TNF-α and IL-4 were significantly elevated in C. sinensis-induced liver fibrosis, which is consistent with previous studies." (PMID 36693049, 2023). "This action on TAB2, which recognizes K63-linked ubiquitin chains of RIP1 in TNF-α signaling or TRAF6 in IL-1β signaling, consequently inhibits the TAK1-MAPK cascade, a pathway critical in liver fibrosis progression." (PMID 37867509, 2023). "Second, TNF-α/IL-1β pretreatment enhanced the efficacy of hADSCs in the improvement in hepatic function and liver fibrosis in BDL mice and increased the ability of hADSCs to inhibit HSC activation." (PMID 37095581, 2023). "Activation of the TLR4-myD88-NFκB signaling pathway, an important pathway associated with hepatic fibrosis and HCC, can lead to the release of downstream inflammatory factors and induce the production of IL-1, IL-6, and TNF-α." (PMID 38074679, 2023). "It has also been demonstrated that cytokines such as IL-13, transforming growth factor (TGF)-β1 and tumor necrosis factor (TNF)-α promote hepatic fibrosis, while cytokines such as interferon (IFN)-γ and IL-10 inhibit hepatic fibrosis." (PMID 38086792, 2023).
liver fibrosis (continued). "In this last viral context, it was shown that hepatic DC acquires the marked ability to stimulate NK cells in a TNF-α-dependent manner in liver fibrosis." (PMID 37342247, 2023). "The high production of TNF-α was previously reported in patients infected by HCV in correlation with liver fibrosis and viral load." (PMID 37342247, 2023). "Serum TNF-α, IL-1β, and IL-6 concentrations in mice with CCl4-induced liver fibrosis were increased in our study, which coincided with the assay results of inflammatory factors in previous studies." (PMID 38116381, 2023). "We established that suppressed hepatic sympathetic nerve activity in HIRI caused by Bmal1 downregulation in the CG resulted in decreased liver fibrosis and inflammatory cytokine levels, including IL-1β and TNF-α." (PMID 37189459, 2023). "As such, the capacity of activated MAIT cells to produce profibrogenic cytokines such as IL17 and TNFα makes these immune cells an attractive target for liver fibrosis resolution." (PMID 37005415, 2023). "Consistent with the marked reduction of hepatic fibrosis by gemigliptin, TNFα and IL1B were significantly lower in the liver and plasma of the gemigliptin-treated group than in the MCD diet–fed group." (PMID 37739179, 2023). "The intrahepatic IFN-γ and TNF-α are crucial proinflammatory cytokines for inducing hepatocyte apoptosis and hepatic fibrosis." (PMID 37775797, 2023). "IL-6, TNF-α and IL-4 are important cytokines involved in liver inflammation, liver injury and liver fibrosis." (PMID 36693049, 2023). "Brg1 also promotes the development of liver fibrosis by modulating liver inflammation via the TNF-α/NF-kB pathway." (PMID 38033027, 2023). "Treatment with Arthrospira, a genus of free-floating filamentous cyanobacteria, increased serum IFN-γ levels but decreased serum TNF-α and IL-6 and hepatic fibrosis and steatosis in CHB patients receiving NA therapy." (PMID 37239062, 2023). "Treatment with TNF inhibition improved systemic inflammation; and liver fibrosis resolved on treatment with the Src kinase inhibitor dasatinib." (PMID 36932076, 2023). "Similar to our previous results in CCl4-induced hepatic fibrosis, the expression of inflammatory factors IL1β and TNFα was significantly decreased in the livers of myeloid-specific RBP-J knockout mice with NAFLD in this study." (PMID 37063432, 2023). "Studies in mice have demonstrated that IL-17 induces liver fibrosis through various mechanisms, including the promotion of HSCs’ myofibroblast-like change and upregulation of TNFα-, TGF-β, and collagen 1α." (PMID 36826975, 2023). "Clinical evidence shows that the level of circulating TNF-α in patients with nonalcoholic steatohepatitis (NASH) is highly correlated with the degree of liver fibrosis." (PMID 36866057, 2023). "Exosomes can reduce liver fibrosis by inhibiting the production of inflammatory factors such as interleukin-6 (IL-6), interleukin-1β (IL-1β) and tumor necrosis factor-α (TNF-α) and pro-fibrotic transforming growth factor-β1 in Kupffer cells." (PMID 37006266, 2023). "Oxymatrine reduces liver fibrosis by limiting the pro-inflammatory cytokines, interleukin-6 and TNF-α generated by carbon tetrachloride and boosting anti-inflammatory factors such as interleukin-10." (PMID 36985782, 2023). "When hepatocytes are exposed to nonalcoholic fatty damage, immune cells release inflammatory factors such as TGF-β, TNF-α and IL-1, resulting in the activation of HSCs and ultimately lead to hepatic fibrosis." (PMID 38086792, 2023). "Untreated STZ/HFD-exposed mice displayed significant increases in NAFLD activity scores, liver triglycerides, NAMPT hepatic expression, plasma cytokine levels (eNAMPT, IL-6, and TNFα), and histologic evidence of hepatocyte ballooning and hepatic fibrosis." (PMID 36809677, 2023). "Targeting the TNF-α signaling pathway is considered a new therapeutic approach for liver fibrosis as TNF-α boosts HSC survival and hepatocyte death and triggers the immune response." (PMID 36978885, 2023).
liver fibrosis (continued). "As inflammation is one of the major etiological agents leading to liver fibrosis, we detected the severity of inflammation using measurements of TNF-α protein expression level and TGF-β and IL-6 gene expression levels." (PMID 36978885, 2023). "The gene expression levels of TNF‐α, IL‐1β and IL‐6 are concomitantly increased, and one such inflammatory reaction has been suggested to play a major contribution to hepatic fibrosis and disruption of lipid metabolism." (PMID 37177862, 2023). "A humanized model of viral-induced liver disease showed the crucial role of GM-CSF in liver fibrosis by reducing the accumulation of intrahepatic tumour necrosis factor-α (TNF-α)-producing CD206+ macrophages and liver fibrosis upon neutralisation of GM-CSF." (PMID 37376049, 2023). "Meanwhile, TGF-β can synergize with IL-6, TNF-α, or IL-1β to accelerate the development of hepatic fibrosis." (PMID 38074148, 2023). "They will recruit other inflammatory cells producing mediators [IL-1β, IL-6, IL-8, tumor necrosis factor (TNF)-α], thus creating a vicious circle responsible for perpetuating inflammation and liver fibrosis." (PMID 37928553, 2023). "Studies have demonstrated that TNF-α upregulates the expression of IL-6 in CCl4-induced liver fibrosis." (PMID 37111188, 2023). "NF-κB enhances liver fibrosis by promoting the survival of hepatic stellate cells (HSCs); TNF-α has a regulatory role in extracellular matrix remodeling and liver fibrosis; and TGF-β1, which activates HSC, is the most potent known fibrogenic agonist." (PMID 38033027, 2023). "Malvidin was found to reduce the development of liver fibrosis by inducing hepatic stellate cell apoptosis and to inhibit TNFα and interleukin (IL)-1β secretion from activated macrophages." (PMID 36232316, 2022). "The mechanism of silibinin in liver fibrosis is mostly concentrated on the TNF signaling pathway and the ErB signaling pathway." (PMID 35890194, 2022). "Liver fibrosis levels were flagrantly higher (p<0.01), and TNF-α, NOD-like receptor protein 3 (NLRP3), caspase-1, interleukin-18 (IL-18), and interleukin-1β (IL-1β) protein or gene expression were manifestly up-regulated (p<0.01)." (PMID 35195182, 2022). "Our data on the effective reduction in M1 polarization markers NOS2, Il6, and TNF-α make siRNA to IRF5 a strong candidate for in vivo modulation of liver fibrosis." (PMID 36010574, 2022). "Consistent with our previous study and the in vitro findings of the present study, we found that DIM significantly reduced the expression levels of IL-1β, IL-6, COX-2, iNOS, and TNF-α in CCl4-induced liver fibrosis." (PMID 36232707, 2022). "Upregulation of TNFR1, one of the TNF signaling receptors, was correlated with incident liver fibrosis." (PMID 35942372, 2022). "For different subtypes of NAFLD, we found significant associations of CRP, IL-1β, and TNF-α with NASH and hepatic fibrosis." (PMID 35603224, 2022). "TNFα can have a crucial role in hepatic fibrosis, alcoholic hepatitis as well as elevation of liver enzymes." (PMID 36518124, 2022). "TNFα is an inflammatory cytokine contributing to liver inflammation and, if enduring, this leads to liver fibrosis and eventually cirrhosis." (PMID 35215790, 2022). "AIH is characterized by aberrant production of proinflammatory cytokines including interferon (IFN)-γ and tumor necrosis factor (TNF)-α, which are factors inducing hepatic fibrosis and hepatocytes apoptosis." (PMID 35509689, 2022). "BBR reduced hepatic fibrosis by stimulating collagen breakdown through lowering tumor necrosis factor-alpha (TNF-α) and TGF-β1 expressions and enhancing matrix metalloproteinase (MMP)-2 concentrations." (PMID 35744831, 2022). "The decrease in pro-inflammatory cytokines (IL-6, IL-1β, and TNF-α) is accompanied by regression of liver fibrosis in CCl4-intoxicated rats." (PMID 35881285, 2022).
liver fibrosis (continued). "The levels of pro-inflammatory cytokines (IL-1β, IL-6, and TNF-α) showed a significant (P < 0.05) increase after 5 and 9 weeks of hepatic fibrosis induction in rats compared with normal control rats." (PMID 35881285, 2022). "The expression of TNF-α increased markedly in the hepatocytes surrounding the central vein and the hepatocytes surrounding the portal area upon induction of liver fibrosis." (PMID 34894966, 2022). "Inhibition of TNF pathway can reduce inflammatory stimulation and inhibit the formation of liver fibrosis." (PMID 35330838, 2022). "A potential synergistic effect of TNFα and IL-17 in periostin-mediated collagen deposition has been described in liver fibrosis." (PMID 35056404, 2022). "In chronic inflammation, such as in liver fibrosis, pro-inflammatory cytokines including TNFα and IL-17 are elevated and continue to drive periostin production, and thus, fibrosis of the liver." (PMID 35056404, 2022). "Analyzing the results of network pharmacology, the oxidative stress, inflammation, and the related pathways (primarily the TNF signaling pathway) were identified as the potential mechanism of HJRG against liver fibrosis." (PMID 35942372, 2022). "The results showed that FA inhibited the proliferation and migration of LX2 cells and adjusted the expression of MMP-1, TIMP-1, COLI, α-SMA, TNF-α, IL-6 and IL-1β as well as promoted collagen metabolism to show potential in anti-hepatic fibrosis." (PMID 35035671, 2022). "The Huangjia Ruangan granule can effectively inhibit liver fibrosis through antioxidation, suppressing liver inflammation by regulating the TNF/MAPK and NF-κB signaling pathways, thereby preventing the effect of liver fibrosis." (PMID 35942372, 2022). "TNFα is a key player involved in HSC survival, hepatocyte death, and immune cell activation, all of which are associated with advanced liver fibrosis." (PMID 36446766, 2022). "TNF-α is the accelerator that promotes the progression of hepatic steatosis to steatohepatitis and ultimately to liver fibrosis." (PMID 35422858, 2022). "Based on the CCl4-induced rat model of liver fibrosis and TNF-α stimulated cell model of HSCs, we demonstrated that VDR regulated progression of liver fibrosis and cell function of HSCs with the participation of NF-κB signaling pathway." (PMID 35043727, 2022). "Regarding the mechanism of action of J2H-1702 during liver fibrosis, TNF showed the greatest expression change following J2H-1702 administration in TGF-β1-treated LX2 cells according to RNA-seq analysis." (PMID 36446766, 2022). "IL-6 and TNF-α enhanced the release of TGF-β1 to activate HSCs and cause fibrosis, suggesting that TNF-α and TGF-β1 upregulation occurred prior to liver fibrosis induction." (PMID 35840761, 2022). "Our results also showed that CRP, IL-1β, and TNF-α were significantly associated with non-alcoholic steatohepatitis (NASH) and hepatic fibrosis." (PMID 35603224, 2022). "It is reported that pro-inflammatory macrophages, also known as Kupffer cells (KC), can stimulate or dismantle liver fibrosis by secreting cytokines such as tumor necrosis factor-α (TNF-a) and interleukin-1β (IL-1β) in the liver." (PMID 35295576, 2022). "In a thioacetamide- and leptin-induced liver fibrosis model, DCs activated hepatic stellate cells, NKT cells, and T cells by producing TNF-α, thus promoting the progression of liver fibrosis." (PMID 36032154, 2022). "Our study identified the TNF signaling pathway as the main signal pathway in the treatment of liver fibrosis with HJRG." (PMID 35942372, 2022).